TMPRSS11D (transmembrane serine protease 11D)
Description:
May play some biological role in the host defense system on the mucous membrane independently of or in cooperation with other substances in airway mucous or bronchial secretions. Plays a role in the proteolytic processing of ACE2. Proteolytically cleaves and activates the human coronavirus 229E (HCoV-229E) spike glycoprotein which facilitate virus-cell membrane fusions; spike proteins are synthesized and maintained in precursor intermediate folding states and proteolysis permits the refolding and energy release required to create stable virus-cell linkages and membrane coalescence. Preferentially cleaves the C-terminal side of arginine residues at the P1 position of certain peptides, cleaving Boc-Phe-Ser-Arg-4-methylcoumaryl-7-amide most efficiently and having an optimum pH of 8.6 with this substrate.
Synonyms: HAT; ASP
Tractability: Small molecule: a high-quality ligand is known; it belongs to a druggable protein family. Antibody: its Gene Ontology location is reachable by antibodies, with high confidence; UniProt places it where antibodies can reach, with medium confidence; UniProt predicts a signal peptide or a membrane-spanning region. PROTAC: a small molecule that binds it is known.
Target class: Enzyme; Protease; Serine protease
Gene: Protein-coding gene on chromosome 4 (67,820,876 to 67,884,002, reverse strand). Ensembl gene ENSG00000153802.
Subcellular location: Cell membrane; Secreted (Transmembrane protease serine 11D catalytic chain)
Gene Ontology:
Molecular function: protein binding; peptidase activity; serine-type peptidase activity; serine-type endopeptidase activity
Biological process: proteolysis; protein processing; respiratory gaseous exchange by respiratory system
Cellular component: extracellular exosome; extracellular region; plasma membrane
Genetic constraint (gnomAD): Loss-of-function variants: 29 observed, 40.59 expected, observed/expected ratio (o/e) 0.71, 90% interval 0.53 to 0.97. The upper end of that interval is the gene's LOEUF score, 0.97, which puts it in group 4 of 6, group 1 being the genes least tolerant of losing a copy. Missense variants: 406 observed, 459.18 expected, observed/expected ratio (o/e) 0.88, 90% interval 0.81 to 0.96. Synonymous variants: 166 observed, 162.03 expected, observed/expected ratio (o/e) 1.02, 90% interval 0.9 to 1.16.
Homologues: Orthologues: chimpanzee TMPRSS11D (99% identical), macaque TMPRSS11D (92% identical), dog TMPRSS11D (79% identical), pig TMPRSS11D (78% identical), rabbit TMPRSS11D (74% identical), guinea pig TMPRSS11D (69% identical), rat Tmprss11d (67% identical), mouse Tmprss11d (67% identical), zebrafish st14a (30% identical), Drosophila melanogaster Sb (29% identical), zebrafish st14b (29% identical), tropical clawed frog tmprss12 (24% identical), and 4 more. Paralogues in human: TMPRSS11F (41% identical), TMPRSS11A (40% identical), TMPRSS11E (39% identical), TMPRSS11B (38% identical), HPN (30% identical), TMPRSS2 (30% identical), TMPRSS3 (29% identical), ST14 (28% identical), TMPRSS13 (27% identical), TMPRSS6 (27% identical), TMPRSS7 (26% identical), TMPRSS15 (26% identical), and 5 more.
Diseases named in the same sentence as TMPRSS11D in open-access papers:
TMPRSS11D is named in the same sentence as 18 diseases in open-access papers, as found by Europe PMC text mining. Sharing a sentence is not in itself a finding about the gene and the disease. The quoted sentences say what the papers report.
influenza (5 papers, 2012 to 2025). An acute viral infection of the respiratory tract, occurring in isolated cases, in epidemics, or in pandemics; it is caused by serologically different strains of viruses (influenzaviruses) designated A, B, and C, has a 3-day incubation period, and usually lasts for 3 to 10 days. "Using the Human Cell Atlas consortium respiratory single-cell RNA-seq data (reflecting the transcriptome of uninfected cells), we compared the expression of proteases previously identified to activate influenza HA: TMPRSS2, TMPRSS4, matriptase/ST14, HAT/TMPRSS11D, and furin." (PMID 40882005, 2025).
viral infection (4 papers, 2021 to 2025). "NHBE and HSAEC cells express ST14 and TMPRSS11D, and both are mildly upregulated in the presence of the viral infections." (PMID 37821447, 2023).
non-small cell lung carcinoma (3 papers, 2017 to 2020). A group of at least three distinct histological types of lung cancer, including non-small cell squamous cell carcinoma, adenocarcinoma, and large cell carcinoma. "However, increased expression levels of a similar type II transmembrane serine protease, TMPRSS11D, were found to be a significant non-small cell lung cancer survival predictor." (PMID 32625238, 2020).
squamous cell carcinoma (3 papers, 2014 to 2021). A carcinoma arising from squamous epithelial cells. "TMPRSS11D, also called human airway trypsin-like protease (HAT), belongs to the differentially expressed in squamous cell carcinoma (DESC) subfamily." (PMID 28086212, 2017).
Kawasaki disease (1 paper, 2020). A rare inflammatory disease characterized by an acute febrile, systemic, self-limiting, medium-vessel vasculitis primarily affecting children. "Furthermore, TMPRSS11D has been indicated as possible target gene of miRNAs, comprising biomarkers of Kawasaki disease, further linking SARS‐Cov‐2 receptors to Kawasaki disease." (PMID 32970391, 2020).
lymphoma (1 paper, 2011). A malignant (clonal) proliferation of B- lymphocytes or T- lymphocytes which involves the lymph nodes, bone marrow and/or extranodal sites. "Likewise all Tmprss11d−/− females presented with lymphoma, whereas this was observed only in three Tmprss11d+/+ females." (PMID 21853097, 2011).
cancer (8 papers, 2017 to 2024). A tumor composed of atypical neoplastic, often pleomorphic cells that invade other tissues. "The role of TMPRSS11D in cancer has been investigated during squamous cell carcinogenesis." (PMID 28086212, 2017). "Specifically, ACE2, TMPRSS2, CLEC4M, DPP4 and transmembrane protease serine 11D (TMPRSS11D) were analyzed by assessing their RNA expression levels in different body districts and in different cancer types." (PMID 32970391, 2020). "Through MSP, TMPRSS11D can activate the MSP-RON signaling pathway in the respiratory tract, a signaling pathway involved in invasive growth of different types of cancer." (PMID 28086212, 2017). "Future clinical studies should investigate the role of other HAT/DESC subfamily members in NSCLC, and in vitro functional studies are needed to decipher the differential roles TMPRSS11D plays in various types of cancer." (PMID 28086212, 2017).
infection (6 papers, 2021 to 2025). The state of being infected such as from the introduction of a foreign agent such as serum, vaccine, antigenic substance or organism. "Based on the observations in this study, we propose a model in which TMPRSS2 and TMPRSS11D mediate proteolytic activation at the viral entry step and facilitate trypsin-independent infection by RVAs in MA104 cells." (PMID 33762412, 2021). "We identified TMPRSS2 and TMPRSS11D as host TTSPs that mediate trypsin-independent and multicycle infection by human and animal RVA strains." (PMID 33762412, 2021). "We suggest a viral-induced coagulation mechanism, in which prothrombin is activated by infection-induced transmembrane serine proteases, such as ST14 and TMPRSS11D, on NHBE cells." (PMID 37821447, 2023). "We also found that TMPRSS2 and TMPRSS11D promote the infectious entry of immature RVA virions, but they could not activate nascent progeny virions in the late phase of infection." (PMID 33762412, 2021).
heart diseases (1 paper, 2019). "Further studies are needed to clarify the function of Tmprss11d in heart diseases." (PMID 30939728, 2019). "However, there has been no study in which the association between Tmprss11d and heart diseases was examined." (PMID 30939728, 2019).
TMPRSS11D also shares sentences with these, for which no sentence is quoted: psoriasis (2 papers); respiratory diseases (2); tumor (2); asthma (1); cholestasis (1); diffuse large B-cell lymphoma (1); endometrial cancer (1); lupus (1); medulloblastoma (1).